Y_RNA (Y RNA )
Gene: Miscellaneous RNA gene on chromosome X (19,985,058 to 19,985,159, reverse strand). Ensembl gene ENSG00000206663.
Homologues: Orthologues: chimpanzee Y_RNA (98% identical), macaque Y_RNA (97% identical). Paralogues in human: RNY3 (90% identical), Y_RNA (90% identical), Y_RNA (89% identical), Y_RNA (88% identical), RNY3P1 (87% identical), Y_RNA (87% identical), Y_RNA (86% identical), Y_RNA (85% identical), RNY3P14 (84% identical), RNY3P9 (84% identical), Y_RNA (84% identical), RNY3P16 (83% identical), and 98 more.